CCL3 (C-C motif chemokine ligand 3)
Diseases named in the same sentence as CCL3 in open-access papers (continued):
Sharing a sentence is not in itself a finding about the gene and the disease.
infection (continued). "For example, Ebola virus (EBOV) infection of monocytes results in strong induction of inflammatory cytokines including IL-6, IL-8, and chemokines CCL3/MIP-1a and CCL4/MIP-1b, with downregulation of class II MHC expression." (PMID 34239884, 2021). "Further, in the acute phase of infection CCL3 protein levels were increased in the cardiac tissue and, although reduced, CCL3 expression persisted elevated in the chronic infection." (PMID 32194558, 2020). "Because chemokines CXCL1 and CCL3 are known to be important for neutrophil migration, we next measured the levels of CXCL1 and CCL3 in the peritoneal lavage after 3 h of infection." (PMID 33193308, 2020). "CCL5 and CCL3 are both chemotactic cytokines that specifically attract T-cells and macrophages to the site of infection." (PMID 32752138, 2020). "The high secretion of CXCL1 and CCL3 in ECD mice leads to the recruitment of more innate immune cells to the site of the infection increasing the possibility of having adverse pathological outcomes." (PMID 32958779, 2020). "But in contrast to the other factors, CCL3 was actually increased in the majority of cell lines post LOAd infection." (PMID 32355275, 2020). "Upon infection with influenza virus, production of cytokines and chemokines including CCL3, CCL4, and CCL5 from respiratory epithelium recruits γδ T cells at the site of infection in a CCR5 receptor-dependent fashion." (PMID 33183352, 2020). "One-week post infection, infected ECD mice produced significantly higher levels of CXCL-1 and CCL3 compared to the other groups (p < 0.0001, p < 0.01 respectively), which then decreased 2 weeks post infection." (PMID 32958779, 2020). "Levels of TNF-α and CCL2 were significantly elevated from pre-clinical to early-stage infection, and IL-6, IL-12b, CCL3, CCL12, and ISG15 levels were significantly elevated from pre-clinical to late-stage infection." (PMID 31790513, 2019). "Transcripts encoding the chemokines CCL2, CCL3 (MIP-1α), IL8, and CXCL13 showed the greatest abundance 24 h after infection with either Makona or RESTV." (PMID 31689981, 2019). "Since infection-primed ADAPko NK cells exhibited impaired production of the phagocyte attracting chemokines CCL3, CCL4, and CCL5 we compared the number of monocytes and neutrophils in the spleen of Lm infected animals." (PMID 32038647, 2019). "IAV infection increased the mRNA expression at day 3 post-infection (105 PFUs) of IL-6, CCL3, CXCL2, and G-CSF, IL-1β and TNF-α (p < 0.05)." (PMID 30787331, 2019). "The significance of CCL3 in protecting against NTHi‐induced OM in mice is already known, and our data on CCL3 levels in both middle‐ear fluids and serum suggests its role in inhibiting the infection of NTHi." (PMID 30265765, 2019). "Regarding the contribution of CCL3 to hRSV infection, it was shown that equivalent to CCL5, CCL3 displays a biphasic expression both for mRNA and protein, at day 1 and 7 post-infection." (PMID 30936869, 2019). "In particular, CCL3/MIP-1α is regarded as a critical mediator of host defense against A. fumigatus infection due to several studies of animal infection models." (PMID 30563459, 2018). "By contrast, infection with the ΔgliP mutant caused an increase in mRNA levels of CXCL2, CCL3, and CCL4, chemokines that are chemotactic for neutrophils." (PMID 30052103, 2018). "In sera, only the peak concentrations of Cxcl1 (8 h), Ccl2 (8 h), Ccl3 (8 h), IL-1β (4 h), and IL-6 (4–8 h after infection) were significantly elevated in ExoY-infected mice as compared to ExoYK81M-infected mice." (PMID 29734720, 2018). "At 2 h post infection (p.i.), enhanced accumulation of mRNAs for Cxcl1, Cxcl2, Cxcl3, and Cxcl5, as well as Ccl3 and Ccl4, was evident (determined as differentially expressed using a 5% FDR)." (PMID 29636754, 2018). "Accordingly, the expression of the receptors for Ccl3 and Cxcl12, Ccr1 and Cxcr4, respectively, were significantly upregulated by the interaction of low diet and infection (p < 0.05)." (PMID 28397794, 2017).
infection (continued). "After super-infection, mRNA levels of IL-6, TNFα, CCL3 and CCL5 were substantially increased, especially at 8 h p.i.." (PMID 28195157, 2017). "The mRNA expression levels of the chemokines Ccl3 and Cxcl12 and the levels of Igf1 in thymocytes were clearly upregulated due to protein malnutrition or infection conditions separately (Ccl3 p < 0.01; Cxcl12 p < 0.05 and Igf1 p < 0.001)." (PMID 28397794, 2017). "Infection of GM-BM with ECTV did not stimulate cytokine and chemokine production, with the exception of CCL3/MIP-1α at later stages of infection." (PMID 28604814, 2017). "The role of the CCR5 ligands CCL3, 4, and 5 was also highlighted in another study that reported an abolished NK cell accumulation at sites of infection in CCR5−/− mice." (PMID 28733594, 2017). "IL-8 and CCL3 primarily stimulate chemotaxis of granulocytes, as well as inducing phagocytosis at the site of infection, whereas IL1β is a key mediator of the inflammatory response, being involved in cell differentiation, proliferation and apoptosis." (PMID 27793136, 2016). "Previous study also showed an overexpression of MIP-1α/CCL3 in the kidneys of hamster 4 days after infection with a virulent Leptospira strain." (PMID 27219334, 2016). "Following L. mexicana infection, we show here that 3 days post infection ccl3 mRNAs is induced at the site of infection selectively in neutropenic mice." (PMID 26020515, 2015). "We also show that the expression levels of several chemokines regulated by NF-κB signaling (Ccl2, Ccl3 and Ccl5) were similarly elevated at early infection." (PMID 25116007, 2014). "We also measured higher levels of the monocytes and mo-DCs attracting chemokine CCL3 in H33 treated animals early after infection." (PMID 25474593, 2014). "The chemokines XCL1 and CCL3 (also known as MIP-1α) induce immune responses against pathogen infection." (PMID 25313504, 2014). "In this study, we found that changes in the expression levels of several chemokines (Ccl2, Ccl3 and Ccl5) mirrored those of NF-κB signaling (similarly peaking 32 days post-infection)." (PMID 25116007, 2014). "This is a chemotactic cytokine that is now officially named CCL3 and is the major factor produced by macrophages and it is crucial for immune responses towards infection and inflammation." (PMID 25110402, 2014). "Thirteen days after infection, mRNA expression of CCL3 and CCL7 in the spleens of MyD88−/− was increased by approximately 21 and 61 fold respectively over non-infected MyD88−/−." (PMID 23374751, 2013). "Accordingly, IEC isolated from IFNγ−/− neonatal mice did not significantly upregulate the expression of CXCL9 and CXCL10 during the infection whereas other chemokines such as CCL3, CCL4 and CCL5 were still upregulated." (PMID 24367259, 2013). "CCL3 expression was already elevated by 6 h post-infection compared with that in uninfected (naïve) liver tissue (P<0.03)." (PMID 23300453, 2013). "Upregulation of CXCL10 and CCL3 in the CNS and peripheral tissues after virulent 5746 infection in transgenic mice was reported by our previous works." (PMID 23936115, 2013). "We next determined the levels of the Ccr1 agonists Ccl3, Ccl5, Ccl6, Ccl7, Ccl8 and Ccl9 in Ccr1+/+ and Ccr1−/− kidneys after infection." (PMID 22916017, 2012). "The levels of CXCL1, CXCL10, CCL1, CCL3, IFN-γ, TNF-α and IL-6 were significantly increased in the lungs of RSV-infected IL-10-deficient mice compared to control mice on day 8 post infection." (PMID 22393401, 2012). "Early in infection (∼5 h), IL-8, MIP-1α (CCL3), GM-CSF, IL-1β, IL-17, and CD25 mRNAs were upregulated by γδ T cells." (PMID 21765931, 2011). "For this, wt or perforin-deficient mice were immunized by infection with Lm (then referred to as “memory mice”), and 3 weeks later some animals were treated with anti-CCL3 serum or anti-IFN-γ neutralizing mAb before the challenge infection." (PMID 22241983, 2011).
infection (continued). "Depletion of neutrophils prior to infection, as well as pharmacological or genetic inhibition of CCL3, resulted in a significant decrease in DC recruitment at the site of parasite inoculation." (PMID 20140197, 2010). "This identifies the CCL3 secreted by neutrophils during the first days of infection as a critical chemokine involved in the recruitment/trafficking of dendritic cells, which influences the subsequent development of the immune response." (PMID 20140197, 2010). "CCL3 is an inflammatory chemokine responsible for recruitment of leukocytes to sites of infection, and promotes a Th1 phenotype in lymphocytes." (PMID 20525375, 2010). "We show in vitro, as well as during infection, that the parasite induced the expression of CCL3 selectively in neutrophils from L. major resistant mice." (PMID 20140197, 2010). "This allowed the investigation of the role of neutrophils on DC recruitment at the site of infection, under conditions when CCL3 secretion was neutralized." (PMID 20140197, 2010). "Changes in levels of transcripts encoding CCL3 (MIP1-α), CXCL8 (swine IL-8), and IL-1β were found to be very close to that indicated by SAGE with all declining as the infection progressed." (PMID 22331987, 2010). "Decreased DC recruitment in CCL3−/− mice was corrected by the transfer of wild type neutrophils at the time of infection." (PMID 20140197, 2010). "Most importantly, chemokine genes e.g., Cxcl9, Cxcl10, Cxcl11, Cxcl13, Ccl3, Ccl5 and Ccl12 that exert a chemotactic signal for the immune cell migration to the site of the injury were upregulated at 72 and 96 hr post infection." (PMID 18558011, 2008). "We have previously demonstrated that topical treatment with CCL3/MIP-1α immunomodulator reduced infection by >99% and improved healing in diabetic mice by bypassing impaired FPR signaling and restoring timely neutrophil trafficking, highlighting its potential in diabetic wound care." (PMID 41597195, 2026). "Similarly, after BF.7 infection of M1 macrophages, the administration of IL‐37 led to an approximately 21% decrease in Ccl4 mRNA expression and an approximately 15% reduction in Ccl3 mRNA expression." (PMID 40452816, 2025). "Notably, cytokine family members Ccl2, Ccl3, Ccl4, Ccl5, Ccl7, Ccl9, and Ccl22 were also significantly activated following infection." (PMID 40539063, 2025). "Moreover, CCL3 is critical for antiviral effector (cytotoxic) function of CD8+CTLs due to promoting their migration to the site of infection and inflammatory phenotype (CCR5 and CXCR3, and IFN-γ expression and cytolytic function)." (PMID 41009359, 2025). "The levels of TNF-α, IL-6, IFN-γ, IP-10, MCP-1, and CCL3 were markedly elevated in the vehicle group, indicating that following infection with the influenza viruses, the lung tissues produced a plethora of proinflammatory mediators, thereby establishing an inflammatory milieu within the lungs." (PMID 40283905, 2025). "CCL3/MIP-1⍺ is a chemotactic cytokine produced by cells during infection or inflammation." (PMID 38967888, 2024). "We found that in comparison to the WT, infection with the ▵vapC12 strain enhanced the expression of genes that encode proteins implicated in neutrophil-mediated immunity in the host (Cxcl2, Trem1, S100A8/A9 and Ccl3)." (PMID 38515752, 2024). "Also, molecules such as TIMP-1, KC (CXCL1), and MIP-1 alpha (CCL3) showed inhibition upon E. japonica- infection in MyD88-independent manner." (PMID 38022511, 2023). "As expected, we found that CCL11 together with CCL2, CCL3, and the receptors CCR2, CCR3, and CCR5 were all upregulated in newly-weaned hamster brain tissues after Delta variant infection at 2, 4, and 7 dpi, of which CCL11 and CCR2 were significantly higher at 4 dpi." (PMID 37122119, 2023). "However, even given this limitation, clear trends were observed, with increases in the pro-inflammatory cytokines TNFα and IL-1β, the regulatory cytokine IL-1RA and the chemokines CCL2, CCL17 and CCL3 in the sputum post-infection." (PMID 37012228, 2023).
infection (continued). "In this approach, immunomodulators—primarily proinflammatory cytokines, such as CCL3, or bacterial products, such as N-Formylmethionine-leucyl-phenylalanine (fMLF)—are used to mobilize and activate innate immune responses at the possible site(s) of infection." (PMID 36611992, 2023). "To test our hypothesis, we treated db/db wounds topically with CCL3 (1 μg/wound) prior to infection and assessed its impact on neutrophil response and infection control in diabetic wounds." (PMID 35112667, 2022). "Consistent with the elevated levels of CCL3 observed in LdCen-/- infected neutrophils, a significant increase of DC migration was observed towards supernatants from LdCen-/- infected neutrophils compared to that from LdWT infection." (PMID 35192633, 2022). "Importantly, following LdCen-/- infection, neutrophils showed a much higher level of induction of CCL3 in vitro and subsequently attracted a larger number of DCs compared to LdWT infection." (PMID 35192633, 2022). "Notably, we also observed that neutrophils responding to LdCen−/− parasites in the ear (the site of parasite inoculation) augmented the expression of CCL3 which attracted significantly higher number of dermal DCs 24 h post infection." (PMID 35192633, 2022). "CCL3 topical treatment enhances neutrophil response and infection control in diabetic wound." (PMID 35112667, 2022). "However, dual species infections with the mixture of A. actinomycetemcomitans and T. denticola significantly decreased IL-2, CCL-3/MIP1α, and G-CSF expression levels compared to sterile implants." (PMID 35203495, 2022). "Similarly, while SARS-CoV-2 infection alone induced a minimal expression of the inflammatory chemokines, the IAV single-infection group induced significantly high levels of CCL3, CCL4, CCL5, and CXCL9." (PMID 35107382, 2022). "Importantly, CCL3 treatment significantly enhanced the ability of diabetic wounds to control infection, as demonstrated by nearly a two log-order reduction in the number of bacteria contained in the CCL3-treated db/db wounds." (PMID 35112667, 2022). "CCL3 mRNA levels increased slightly on day 1 and were undetectable on days 5 and 6 after infection." (PMID 33477869, 2021). "Thus, for the first time the role of CCL3 controlling growth of an infectious agent is explored in a model of long-term infection (120 dpi)." (PMID 32194558, 2020). "Therefore, our data demonstrate that TLR-2 and TLR-4 are indirectly associated with neutrophil migration because the lower levels of CXCL1 and CCL3 in KO animals’ infection site led to an impairment in neutrophil migration." (PMID 33193308, 2020). "The cytokines CXCL8, CCL5 (also known as Regulated on Activation, Normal T Expressed and Secreted, RANTES), tumor necrosis factor α (TNF-α), CXCL1/5 and CCL3 released, promote development of a pro-inflammatory state along with the recruitment of other immune cells to the site of infection." (PMID 33102253, 2020). "In the acute phase of infection (28 dpi), the T. cruzi-infected ccl3−/− mice showed an increase in the number of parasite+ areas in the cardiac tissue in comparison with infected ccl3+/+ mice, supporting a role for CCL3 in resistance to acute T. cruzi infection." (PMID 32194558, 2020). "Neutrophils also produce CC-chemokine ligand 3 (CCL-3) early after infection with Leishmania parasites, and this chemokine promotes the recruitment of macrophages and DCs to the site of infection that participate in the phagocytosis of apoptotic infected neutrophils." (PMID 32656269, 2020). "Thus, Mφ were required in order to observe a predominant secretion of IL-6 and TNF-α in response to PA, PB and ST infection, and CCL3 in response to PA." (PMID 31412039, 2019). "In our study, we observed an increase in hepatic monocyte/macrophages during SIV infection that correlated with both inflammatory (TNFα, CCL3) and fibrosis (TGFβ) mediators suggesting multiple, and maybe even opposing, roles during infection." (PMID 29466439, 2018).
infection (continued). "On the basis of these findings and ours, we propose that ISP2 inhibits the activity of serine peptidases of host cells that are recruited early in infection, and that this interaction facilitates the changes we observed in CCL3 secretion and the second wave of cellular recruitment and activation." (PMID 29097502, 2018). "Indeed, we found the proinflammatory cytokines IL-1β, TNF, and Ccl3 reduced in BAL-f of ExoY-infected mice as compared to ExoYK81M-infected mice at 2–4 h after infection." (PMID 29734720, 2018). "As infection progressed, we detected a robust upregulation of genes encoding cytokines and chemokines (CCL2, CCL3, IL1B, CXCR1, IL1RN) as well as granulocyte associated transcripts (TLRs 1-4, SPI1, S100A8, S100A9, CD177), which correlated with the higher numbers of granulocytes 5 DPI." (PMID 28852031, 2017). "However, ECTV encodes vCCI decoy receptor, EVM1, which is an abundantly secreted glycoprotein during infection and can bind the CC chemokines to form highly stable complexes with CCL3 and CCL5." (PMID 29312229, 2017). "Interestingly, infection with the ST17 strain resulted in higher plasma levels of the chemokine CCL3 than those observed in the other groups." (PMID 27527222, 2016). "When comparing the relative expression of these chemokines in sorted neutrophils versus whole kidney homogenates, neutrophils appear to be a significant source for Ccl3 and perhaps for Ccl6 and Ccl9 in the kidney after infection, suggestive of a positive feedback loop of neutrophil chemoattraction." (PMID 22916017, 2012). "However, these cells clearly were responding to the infection, as Ccl2, Ccl3, and Il1β were upregulated in expression compared to cells from non-infected mice." (PMID 23248776, 2012). "In a previous study using mice intravenously inoculated with Lm as an infection model, we have shown that innate phagocytes can be activated by the Macrophage Inflammatory Protein 1α (MIP-1α/CCL3) that is secreted by memory CD8+ T cells upon antigen-driven reactivation." (PMID 22241983, 2011). "CCL3 was produced biphasically, in both the early (day 1) and late (day 6–7) stages of infection." (PMID 20195359, 2010). "In our model, some chemokines reported to be part of the "1st and 2nd waves" of chemokine expression by DC cells, specifically Xcl1, Cxcl9, Cxcl16, Ccl1, Ccl2, Ccl3, Ccl4, Ccl5, Ccl7 and Ccl8 are expressed at increased levels in lung i.n. samples at 3 weeks post-infection." (PMID 20942964, 2010). "Thus, while the balance between the chemokines CCL21 and CCL3 changes during infection, the receptors for these chemokines, CCR7 and CCR5 respectively, are not altered on the naive T cells in the absence of cognate antigen." (PMID 19578440, 2009). "We therefore conclude that MIP-1α/CCL3 is produced during infection with S haematobium." (PMID 19852800, 2009). "Therefore, mRNA levels for CCL21 and CCL3 within the lymph node, during infection were measured by RT-PCR." (PMID 19578440, 2009). "This conclusion is supported, at least in part, by the results of Sukumaran and colleagues, who reported the upregulated expression of chemokine genes encoding CXCL1, CXCL2, CXCL3, CXCL8, CCL3, CCL4 and CCL20 after infection of PMN with Anaplasma phagocytophilum." (PMID 17875202, 2007). "Similarly, stimulation of M1 macrophages with an NF‐κB activator and subsequent infection with Omicron BA.5 resulted in increased production of the inflammatory factors CCL3 and CCL4; nevertheless, intervention with IL‐37 significantly attenuated the expression of these chemokines." (PMID 40452816, 2025). "Infection with HTLV-1A/CoI-L resulted in low overall frequency of monocytes, DCs, and neutrophils producing IL-10, with elevated frequencies of those producing TNF-α in both compartments, linked to high expression of IL-6, CCL2, and IL-33 in blood and of MMP1, IL-1β, CCL3, and CCL19 in the lung." (PMID 41006234, 2025).